NOTCH1 (notch receptor 1)
Diseases named in the same sentence as NOTCH1 in open-access papers (continued):
Sharing a sentence is not in itself a finding about the gene and the disease.
cancer (continued). "Our bioinformatic analysis unexpectedly identified MYC signaling as an alternative pathway for cancer cell proliferation upon the knockdown of both MYB and NOTCH1." (PMID 36879115, 2023). "With the knockdown of the upstream inhibitory target DNMT1, the highly expressed MEG3 shows high potential for cancer inhibition, including inhibiting cancer cell proliferation and promoting apoptosis, and inhibiting EMT through Notch1 signaling pathway." (PMID 37901333, 2023). "We found that a number of signaling networks and their components such as PI3K/Akt/mTOR, MMP‐2 and 9, Wnt/‐catenin, PARP, MAPK, NF‐κB, Caspase‐3/8/9, Bax, Bcl2, Smad4, Notch1, STAT3, Nrf2, and ROS signaling can be regulated in cancer cells by phytochemicals." (PMID 37132286, 2023). "Notch1 signaling was activated in TGFβ2‐stimulated EMT, and played a significant role in cancer metastasis and recurrence." (PMID 37533228, 2023). "In concert with these results and the demonstration that silencing WDR5 decreases NOTCH1 expression, we found that, like MUC1-C, WDR5 is necessary for the self-renewal of cancer cells." (PMID 37821650, 2023). "Our results indicated NOTCH1, NOTCH3, FLCN, SOD1, SOD2, NF1, and TLR4 as upregulated proteins in different cancer types highlighting their role in cancer progression." (PMID 35001007, 2022). "The decreased expressions of β-catenin-dependent cancer stem cell markers (CD44, EpCAM, Notch 1, and Oct4) advocated for the inhibition of metastatic progression." (PMID 36362950, 2022). "We observed that the expression of 26 cancer driver genes is downregulated by fb-PMT, representative examples of which include EGFR, NOTCH1/2, MAPK1, CCND1, and BRAF." (PMID 36879662, 2022). "By contrast, the p71/p72 isoforms inhibit Notch1 activity by ubiquitylating N1ICD, leading to EMT reversion and reduced cancer cell migration." (PMID 35457181, 2022). "A functional synergism was also observed between Notch1 and SMAD3 in the regulation of EMT and cancer cell migration." (PMID 35457181, 2022). "In addition, the iron channel protein PIEZO2 and its target protein NOTCH1/2 were upregulated (GEO database: GSE120194) 14 PIEZO is a mechanically sensitive channel protein that has recently been implicated in the development and progression of various cancers." (PMID 34976193, 2022). "HSP prevented BON cancer cell proliferation and induced cancer cell death by decreasing achaete-scute complex-like 1(ASCL1), chromogranin A (CgA), and enhanced Notch 1 expression." (PMID 35128104, 2022). "Important signaling pathways, such as NF-κB, PI3K/Akt/mTOR, Notch 1, Wnt/β-catenin, and YAP, have been considered as therapeutic targets for patients with cancer." (PMID 35517785, 2022). "Collectively, these results provide evidence of positive crosstalk between the Notch1 and BAI1-Rac1 pathways upon stimulation with apoptotic cancer cells." (PMID 36241874, 2022). "In particular, cluster 11 had high expression levels of cancer stem cell (CSC) marker genes, including NOTCH1, KLF4, CD44, EPAS1, and MYC." (PMID 36618022, 2022). "The expression of EGFR and Notch1, a member of the NOTCH family of transmembrane proteins that regulate many basic processes essential for cancer development and progression, was significantly associated with poor survival outcomes in TBSCC." (PMID 35562926, 2022). "In cancer cells, BRD4 can bind to Jagged-1 and NOTCH1 promoters, increasing the gene expression of both NOTCH components and thus leading to NOTCH pathway activation." (PMID 35215234, 2022). "Reactivation of Notch1 results in enhanced CD8+ T-cell effector functions, anti-cancer response and resistance to immunosuppression." (PMID 36090975, 2022).
cancer (continued). "NOTCH1 and NOTCH4 play a key role in the EMT pathway to increase the migration and invasion of cancer cells to other body organs such as the lungs and especially the liver." (PMID 35928368, 2022). "For example, in our RPPA dataset, C-PAC increases levels of NOTCH1 in JHAD1 cells, which is counterintuitive given cancer cell death induction; however, Western blot analysis revealed that C-PAC specifically decreases the intracellular cleaved form of NOTCH1." (PMID 35267943, 2022). "Our results show that Cbl-b inhibitors, by inducing Notch1-dependent CD8+ T-cells responses, have a promising potential as anti-cancer single-agents and as combinatorial immunotherapy with checkpoint inhibitors." (PMID 36090975, 2022). "Our data further reveal that NUMB p65/p66 isoforms increase Notch1 activity, and N1ICD works in concert with SMAD3 to promote EMT and thus enhance cancer cell migratory abilities." (PMID 35457181, 2022). "These cytokines contribute to pro-cancer inflammation, which is known to aggravate cancer progression, and activate several pathways, such as epithelial-mesenchymal transition (EMT), Notch1 signaling, and angiogenesis." (PMID 34131208, 2021). "Downregulation of Notch1 was further observed in MCF7 and HEPG2 cancer cells as well as in both liver and kidney tissues, two organs known for high selenium retention." (PMID 33802299, 2021). "Amongst the cancer-relevant microRNAs, miR-582-5p suppresses cell growth and tumorigenesis by inhibiting the expression of oncogenes, including AKT3, MAP3K2 and NOTCH1." (PMID 33670427, 2021). "Particularly, concurrent overexpression of the oncogenic genes Twist1, Snail1, and Notch1 strongly induces EMT and enhances stemness, thereby inducing cancer and metastasis." (PMID 34922602, 2021). "Notch1-dependent activity in the PI3k-Akt pathway via DLL4 leads to cell migration and invasive cancer." (PMID 36643842, 2021). "Although EYS has not previously been investigated in the context of prognosis, the adverse prognostic impact of APC, NOTCH1, ARID1A, and filamin A has been reported in other cancer types." (PMID 33801954, 2021). "Notch1 plays a key role in epithelial-mesenchymal transition (EMT) and in the maintenance of cancer stem cells." (PMID 33922104, 2021). "Finally, in cancer stem cells (CSCs) of tumorspheres from SW620, the combined treatment of AHCC and ETAS caused a significant reduction in the gene expression of LGR5 and Notch1, opening new perspectives for the testing of these compounds in association with conventional chemotherapy." (PMID 34959725, 2021). "Manassantin and arctigenin are plant lignans with anti-cancer activities, and regulates multiple important signaling pathways, including NF-kappa B, PI3K/Akt/mTOR, and MAPK/ERK, Notch-1, and p38." (PMID 34490085, 2021). "The differences in cell differentiation and cancer-related genes (AFP, NOTCH1, CSF1, NOTUM, TGFβ, and vimentin genes) implied different biological characteristics between cells cultured in the 3D and 2D models." (PMID 32582546, 2020). "On the basis of previous studies of NANOG regulators in various cancers, we chose the following protein regulators for further analysis: AGR2, KLF4, NOTCH1, OCT4, and SOX2." (PMID 32733958, 2020). "It is said that tumor-educated B (TEB) cells are able to enhance cancer progression via the activation of IL-1β/HIF-2α and subsequent induction of Notch1." (PMID 32380783, 2020). "Pathways related to nervous system development (FDR = 5.8 × 10−8) were enriched for the PID-N genes ASCL1, CTNNB1, ID2, SUFU, and TERT that have known roles in cancer, complementing the PID-C genes NOTCH1, PTEN, and RHOA that also have known cancer roles." (PMID 32024854, 2020). "The antibody OMP21M18, a humanized IgG2 antibody, blocking the interaction of DLL4 with NOTCH1 and NOTCH4 and had been tested as a cancer stem cell agent in a Phase-I trial in patients with previously treated solid tumors." (PMID 32796631, 2020).
cancer (continued). "Notch receptors have been implicated as oncogenic drivers in a number of different human cancers, including T-ALL, which shows increased Notch1 activity in about 60% of cases, due to activating Notch1 mutations or alterations in the FBXW7 gene." (PMID 33071287, 2020). "The authors show that frequent NOTCH1 gene amplification and overexpression render CAFs resistant to the UVA-induced DNA damage response (DDR) and promote cancer/stromal cells expansion, which can be reversed by NOTCH inhibition." (PMID 33046701, 2020). "It has been reported that high NOTCH1 and NOTCH3 expression levels are related to poor OS rates in cancer." (PMID 33479597, 2020). "Knockdown of TRIB3 in radioresistant MDA-MB-231 TNBC cells decreased Notch1 activation, as well as the CD24-CD44+ cancer stem cell population, and sensitized cells toward radiation treatment." (PMID 30678233, 2019). "Here, Notch4 activates NF-κB, boosting cancer cells growth and EMT; Notch1 promotes EMT, invasion and cell migration and EMT-like prostate cancer cells display a CSC phenotype." (PMID 30873026, 2019). "Examples include patients with high level of ZFAS1 with low expression of NOTCH1, one of the important elements of the pathway described in the context of EMT and cancer-initiating cells." (PMID 31010087, 2019). "Cancer stem cells usually interact with the TME through the activation of self-renewal and stem cell-related pathways, such as the Notch-1 and PI3K pathways." (PMID 31906017, 2019). "Since higher expression of NOTCH1 was observed in NSCLC tissues and cell lines than that in para-carcinoma tissues and human bronchial epithelial cell line BEAS-2B, we next examined the impact of NOTCH1 overexpression on NSCLC cell growth and invasion." (PMID 31170211, 2019). "In our study, we assessed the expression of NOTCH1 in NSCLC tissues and para-carcinoma tissues respectively and found that NOTCH1 was down-regulated in NSCLC tissues, which was accordant with previous studies." (PMID 31170211, 2019). "In this study, we showed that nuclear NOTCH1 expression was negatively correlated with malignancy status, this means that loss of nuclear NOTCH1 expression, the presumably active protein, might favor neoplastic progression from precursor cervical lesions (CIN) to cancer (ICC)." (PMID 29721172, 2018). "During the process of dedifferentiation, multiple genes that were demonstrated to be pivotal in cancer stem cell properties were induced, including PDGFRB, NOTCH1, JAG1, HES1, and HEY1 of the Notch signaling, SNAI1 and SNAI217–20." (PMID 29991717, 2018). "Fringe modulation of ligands will be of significance in understanding Notch activity in cancer stem cell asymmetric division where LFNG, DLL1 and NOTCH1 are present in the same cell." (PMID 29629872, 2018).
cancer (continued). "Notch1 signaling is one such pathway, upstream of AKT signaling, and has been shown to modulate EMT in several cancer types including colorectal adenocarcinoma." (PMID 30038258, 2018). "Further research suggested that CBL0137 exerts an antitumor activity through multiple targets, including facilitates chromatin transcription (FACT), NOTCH1, and heat shock factor 1 (HSF1), in various cancers." (PMID 30581774, 2018). "Crosstalk between Notch1 and EGFR signaling in cell proliferation and cancer expression has been observed in genomics and can be either synergistic or antagonistic depending on the different contexts." (PMID 29321718, 2018). "It is evident that miR-9/9* expression affects many biochemical pathways commonly deregulated in human cancer such as the PI3K/AKT, JAK/STAT, NOTCH1, Wnt/β-catenin, Ras and ERK signaling pathways." (PMID 29755694, 2018). "We also showed that this activation is relevant in mediating the pro-cancer function of DEC1 and that in turn NOTCH1 pathway induces activation of DEC1 expression in a positive feedback loop." (PMID 30158530, 2018). "In parallel, miR-494-3p promotes NOTCH1 signaling and expression of downstream genes involved in EMT and cancer stemness." (PMID 27980227, 2017). "Thus, like TGFβ, Notch1 may have differential roles in cancer initiation and development." (PMID 29170450, 2017). "To figure out expression of Notch1 and NICD1 in HCC cancer tissues and normal tissues in the present study, we carried out qRT-PCR and western blot analysis by extracting their total mRNAs and proteins." (PMID 28507277, 2017). "TDP‐A and VPA significantly induced Notch1 mRNA expression in a dose‐dependent manner in BON, H727, and MZ cancer cell lines at concentrations close to their IC50." (PMID 28776955, 2017). "Genetic or chemical perturbation of NOTCH pathway using shRNA and GSI-XXI showed decrease soft agar colony formation, migration potential and cancer stem-like features of HNSCC cells, highlighting their dependency on NOTCH1 expression." (PMID 27391340, 2016). "Hierarchical Cluster data suggests a much more complex situation of NOTCH1 and HES1 expression correlated with cancer stem cell marker CD44, ALDH1, Slug and SOX2." (PMID 27108536, 2016). "It has been found that mir-34a regulates the expression of NOTCH1 and DLL1 in different types of cancer." (PMID 27039384, 2016). "Recently, many studies has shown several mechanisms associated with rapamycin resistance, which including promyelocytic leukemia (PML) gene, JAK2/STAT5, Notch1 and MAPK mediated resistance to mTOR-targeted therapies in cancer." (PMID 26872016, 2016). "An in vitro spheroid formation assay was performed to examine the cancer stem cell population (CSCs) in HNSCC cell lines (NT8e, CAL27, AW13516, and DOK) expressing a variable level of NOTCH1 expression." (PMID 27391340, 2016). "In contrast, it was recently reported that Jagged-1 and Jagged-2 increase VEGF secretion, and that Notch1 activates hypoxia-inducible factor-1α, the main regulator of VEGF in cancer angiogenesis." (PMID 27846321, 2016). "Emerging evidences have suggested that Notch1 induces increase of MMP-2 and MMP-9 expression that were important in cancer invasion and the extracellular matrix remolding during VM development." (PMID 27793002, 2016). "For example, genes with Motif 1 in Molecular Mechanisms of Cancer pathway include MAPK1, BRAF, SMAD2, FZD5, FZD8, NOTCH1 and LRP1, whereas genes with Motif 2 and/or Motif3 in the same pathway include LRP5, LRP6, MDM2, CTNND1, SMAD3, SMAD4 and SMAD7." (PMID 26040697, 2015). "NOTCH1, a key component present in [ER+|PR+]HER2− tumors, symbolizes the importance of Notch signaling in such cancers, which is an evolutionarily conserved mechanism that mediates communications between cells." (PMID 26404658, 2015). "Our results suggest that the Notch1 signaling axis is upregulated in TNBC and correlates with cancer invasiveness." (PMID 26418877, 2015).
cancer (continued). "Notch1 and N1-ICD-V1754 expression patterns were characterized in cancer cell lines via modulation using EDTA and in human NSCLC tumors." (PMID 25653136, 2015). "In contrast, transcripts encoding several canonical Notch signalling components, including DLL1, JAG1, NOTCH1 and HES2, were down-regulated in cancer cells." (PMID 25864518, 2015). "An increasing number of studies have shown that NOTCH1 plays a critical role in epithelial-mesenchymal transition (EMT), an early step in cancer metastasis." (PMID 26491213, 2015). "Since miR-34a suppresses many oncogenes and cancer stem cell markers including CD44, CDK4, CDK6, c-Met, Notch-1, Notch-2, SIRT1 and DLL1 as its target genes, miR-34a plays important roles in cancer stem cells." (PMID 26580663, 2015). "Collectively, these findings suggest divergent functions of NOTCH1 and NOTCH2 in UC, which have also been observed in other cancers." (PMID 25167871, 2014). "Across the cancer tissues, expression of HES1 mRNA was significantly increased compared to normal bladder, despite the significant downregulation of NOTCH1, NOTCH2 and DLL1." (PMID 25167871, 2014). "siRNA-mediated knockdown of snoRA42 in CD133+ cells led to a significant decrease in transcript levels of the genes, including Oct4, Nanog, Sox2, Notch1, Smo, and ABCG2 compared to scrambled siRNA-treated CD133+ cancer cells." (PMID 24886050, 2014). "These deletions contained known cancer genes based on the Sanger Census cancer gene list, including FGFR3, RECQL4, NOTCH1, PTEN, TSC2, and/or ASPSCR1 which suggested their roles as tumor suppressor genes in the development of HCC." (PMID 25469175, 2014). "Thus, Notch1 depletion may have had a stronger effect than visfatin depletion because the former targeted the proliferation and survival of the cancer stem cell population as well as the bulk cancer cell population." (PMID 24970818, 2014). "We have previously demonstrated that downregulation of DCLK1 can upregulate critical miRNAs in both in vitro and in vivo cancer models and results in downregulation of c-MYC, KRAS, NOTCH1 and EMT-related transcription factors." (PMID 24040120, 2013). "The Notch1 3'UTR harbors predicted miR-34 binding sites, and recent studies in cancer cell systems show that miR-34a directly represses Notch1/2, to slow proliferation or invasiveness." (PMID 22701667, 2012). "We investigated the association of cumulative exposure to these carcinogens with NOTCH1, HIF1A and other cancer-specific proteins in lung tissue from uranium miners." (PMID 23028920, 2012). "It has been documented that hypoxia is clearly involved in the maintenance of cancer stem cell (CSC) phenotype which function through HIF proteins and its downstream gene targets such Oct4, and Notch-1." (PMID 23272057, 2012). "NOTCH1 and NOTCH4 have been recognized as oncogenes in many cancers." (PMID 41561443, 2026). "The relative expression levels of PIK3CA, AKT, PTEN, VEGFA, NOTCH1, and HES1, as the key cellular signaling pathways involved in cancer biology, angiogenesis, and cell survival/proliferation, were investigated to determine the effects of SCC, DOK, and HaCaT products on fibroblasts." (PMID 40729037, 2025). "Mechanistically, Notch1 overexpression upregulates the expression of transcriptional factor YY1 (Yin-Yang 1), which in turn represses ICAM1 expression to prohibit CD8+ T cell-derived granzyme-driven cancer cell pyroptosis and cytotoxicity." (PMID 41271562, 2025). "In cancer stem cells (CSCs) marked as CD44+/CD133+, restoring miR-34 reduced the CSC population by 87% by suppressing their growth and decreased tumor formation by lowering Bcl-2 and Notch1/2 levels." (PMID 40699746, 2025). "Additionally, MDK triggers NOTCH1 and NOTCH2 signaling, pathways known to promote EMT and chemoresistance in multiple cancer types." (PMID 40500394, 2025). "Although NOTCH1 can drive EMT across some cancer model systems, the relationship between NOTCH1 and EMT in SCLC has not been well-defined." (PMID 40627448, 2025).